IL6 (interleukin 6)
Diseases named in the same sentence as IL6 in open-access papers (continued):
Sharing a sentence is not in itself a finding about the gene and the disease.
myocardial infarction (continued). "To disentangle the association of IL6R with inflammation and risk of CHD, we analyzed the association of IL6R haplotypes with circulating levels of inflammatory biomarkers [CRP, fibrinogen, sIL6R, IL6, interleukin 8 (IL8) and TNF-α] and with the risk of myocardial infarction (MI) and CHD." (PMID 25781951, 2015). "Similarly, level of proinflammatory markers (hs-CRP, IL-6, and ICAM-1) and pregnancy associated plasma protein-A (PAPP-A) in serum also clearly display myocardial infarction (MI)." (PMID 25949827, 2015). "Administration of SHED-CM reduced myocardial infarct size as well as decreased apoptosis and inflammatory cytokine levels, such as TNF-α, IL-6, and IL-β, in the myocardium following I/R." (PMID 26542315, 2015). "Serum levels of leptin, IL-6 and CRP were evaluated for 93 Acute Myocardial Infarction (AMI) patients and 102 control subjects." (PMID 22891684, 2012). "It has been demonstrated that inflammatory cytokines, including IL-1β, IL-6, and TNF-α, increase remarkably after myocardial infarction and are involved in the subsequent left ventricular remodeling." (PMID 22792312, 2012). "Unlike CRP and IL-6, suPAR remains stable during acute events like myocardial infarctions and shows minimal circadian variation." (PMID 41480757, 2026). "The combination of CF and BBP significantly reduced the increased IL-6, LDH, and CK levels caused by myocardial infarction; however, CF and BBP alone did not exhibit such pronounced effects on LDH and CK levels." (PMID 39863867, 2025). "Animal studies investigating the effect of RIC in experimental myocardial infarction have demonstrated that RIC, whether completed pre, per or post ischaemia, can lead to reductions in circulating IL-6." (PMID 40336073, 2025). "IL-6 activates the MAPK/ERK1/2 pathway, leading to overexpression of the MMP9, which contributes to extracellular matrix remodeling and fibrosis, processes involved in adverse ventricular remodeling and heart failure following myocardial infarction." (PMID 41511355, 2025). "In this cluster, troponin, a strong independent predictor in myocardial infarction, was positively correlated only with neutrophil or neutrophil-associated inflammatory molecules (NLR, S100A8/A9, NETS and IL-6) but not with ESR, Ferritin, Fibrinogen, and CRP." (PMID 38791147, 2024). "In the study, compared to the first day of myocardial infarction, there was an increase in the titers of interleukin 4 and interleukin 10, obtained 30 days after myocardial infarction, but the titers of IL-6 did not change overtime." (PMID 35837017, 2022). "IL-6 levels in CSF and serum are significantly higher in TBI fatalities compared to non-infectious controls for which the survival time was assumed to be zero such as atraumatic hypoxic brain damage or acute myocardial infarction." (PMID 35226180, 2022). "For example, serum IL-6 can discriminate TBI fatalities from fatalities due to acute myocardial infarctions and diffuse cerebral hypoxias, but not from isolated torso traumas." (PMID 35226180, 2022). "Moreover, pretreatment with atorvastatin significantly reduces plasma IL-6 and TNF-α levels as well as Rho-kinase activity, myocardial infarct size, and cardiomyocyte apoptosis." (PMID 36684592, 2022). "For example, a 1-SD higher baseline serum level for each of IL-6, IL-18, and TNF-α is associated with a 10–25% higher risk of non-fatal myocardial infarction (MI) or coronary heart disease (CHD) death." (PMID 35997393, 2022). "Different IL-6 concentrations between ID/DD genotypes, for example, were found in patients with myocardial infarction but not in control patients who had no history of cardiovascular diseases." (PMID 35886907, 2022). "There was an increase in the titers of IL-4 and IL-10 at D30 after myocardial infarction compared to D1 (P=0.013 and P<0.001, respectively, Wilcoxon test), while IL-6 titers did not change (P=0.31, Wilcoxon test)." (PMID 33495783, 2021).
myocardial infarction (continued). "The effects of IL-6 during acute myocardial infarction and myocardial I/R have not been fully elucidated." (PMID 33428604, 2021). "TNF-α influences the production of other pro-inflammatory cytokines, such as IL-1 β and IL-6, resulting in a negative cycle of pro-inflammatory cytokine production and aggravation of injury after myocardial infarction." (PMID 33503060, 2021). "In addition, a clinical study found that after revascularization of myocardial infarction, inflammatory factors in patients' serum including TNF-α, IL-1β, IL-6, and IL-8 were significantly increased." (PMID 34858542, 2021). "Systemic hs-CRP and IL-6 reduction have not been observed when administrating colchicine directly after acute myocardial infarction." (PMID 32866166, 2020). "We measured and analyzed the immune cells including CD3+ T cells, CD19+ B cells, Ly6G+ neutrophils, F4/80+ macrophages, and inflammatory factors such as IL-1b, Il-6, IL-12, TNFa, and MCP-1 in the heart tissue from different groups at day 7 after myocardial infarction." (PMID 32641103, 2020). "Some inflammatory cytokines, including IL-1, IL-4, IL-6, IL-8, IL-18, and TGF-β1, are involved in the development of ischemic heart disease, myocardial infarction, and heart failure, thus, serving as potential targets for the development of some anti-ischemic therapies." (PMID 32104703, 2020). "In vivo experiments showed that GXV increases the ejection fraction and fractional shortening and reduces the left ventricular mass index and reduces the levels of IL-6, TNF-α and other inflammatory factors in rats with acute myocardial infarction by inhibiting the NF-κB pathway." (PMID 33187508, 2020). "The idea of studying it within the pathophysiology of acute myocardial infarction is related to the role of inflammation in atherothrombosis and to CRP synthesis by hepatocytes, as a result of stimulation by inflammatory cytokines, primarily by IL-6." (PMID 33238444, 2020). "Moreover, aronia berry extract has been shown to reduce blood cardiovascular risk markers such as oxidized-low-density lipoproteins (LDL), C-reactive protein (CRP), IL-6, soluble-ICAM-1, soluble-VCAM-1, and MCP-1 in patients after myocardial infarction." (PMID 31452653, 2019). "Moreover, a multicenter longitudinal study that assessed 955 myocardial infarction survivors from six European cities identified a strong correlation between fibrinogen beta chain (FGB) and IL-6 and worse outcome after exposure to air pollutions." (PMID 31299012, 2019). "Furthermore, in a mouse model of myocardial infarction, TNF-α mRNA, IL-1α, IL-2, IL-4, IL-5, IL-6, IL-10, IL-17A, TNF-α, IFN-γ, and GM-CSF expression were all lower in the infarct area of TLR4-deficient mice compared with wild-type mice." (PMID 30399158, 2018). "These might partially explain the mechanism of why HMP decreases IL-6 and TNF-α in rats with acute myocardial infarction." (PMID 28373886, 2017). "Low dose Omacor® (1 g/day) did not influence plasma IL-6 concentration in patients studied following myocardial infarction, while others reported a lack of effect of Omacor® on sCD40L and MMP-9 concentrations." (PMID 24065166, 2013). "Similarly other studies demonstrated a significant association of IL-6-174G>C polymorphism along with increased levels of circulating serum IL-6 and hs-CRP with myocardial infarction and acute coronary syndrome (ACS)." (PMID 24363620, 2013). "Mechanical stress is associated with myocardial infarction triggering myocardial production of TNF and IL-6, not only in the infracted, but also in the non-infarcted region of the heart." (PMID 17592640, 2007). "Importantly, cytokines, such as IL-1β, IL-6, and IL-8, are known to potentiate both primary hemostasis (formation of platelet plugs) and secondary hemostasis (the coagulation cascade), which, in the setting of CAD, can explain myocardial infarction." (PMID 41156763, 2025).
myocardial infarction (continued). "Taken together with the results of the subgroup analyses, STS did not have a significant effect on lowering the levels of IL-6 for patients with coronary artery disease and ischemic stroke, but it had a significant effect on patients who suffer from unstable angina and acute myocardial infarction." (PMID 40017522, 2025). "Interestingly, IL-1, IL-6, CCL2, and CCL3 expression was reduced, whereas Arg1, IL4Rα, and IL-10 expression were increased in macrophages incubated with exosomes derived from the myocardial infarction group." (PMID 35548775, 2022). "A similar dual effect was confirmed in experimental models of myocardial infarction, where neither IL-6 deletion nor recombinant IL-6 administration affected infarct size, left-ventricular remodeling, or survival in mice after permanent left anterior descending artery (LAD) ligation." (PMID 33770265, 2021). "Importantly, pro-inflammatory cytokine levels are elevated in the myocardium following myocardial infarction (including TNF-α, IL-1β, and IL-6), producing electrophysiological changes, suggesting that the persistent existence of inflammation is an important contributor to arrhythmia." (PMID 32116751, 2020). "Moreover, a meta-analysis of up to 29 population-based prospective studies, IL-6, IL-18, and TNF-α were all found to result in significantly higher relative risks for non-fatal myocardial infarction or CHD death after adjusting for traditional risk factors." (PMID 29750272, 2018). "The current study investigated the effect of HMP on the concentrations of interleukin-6 (IL-6) and tumor necrosis factor-alpha (TNF-α) and observed the relationship between level changes of inflammatory cytokines and ventricular remodeling in rats with acute myocardial infarction (AMI)." (PMID 28373886, 2017). "Likewise, the Framingham Heart Study revealed that elevated baseline levels of TNF-α, IL-6, and CRP in individuals without a history of acute myocardial infarction (MI) are associated with a significantly increased long-term risk of developing HF, irrespective of MI occurrence." (PMID 40814000, 2025). "The sharp fluctuation of IL-6 concentration in leprosy affected person different from normal people has potential for leprosy treatment, and can better predict disease in leprosy early monitoring, as it has been used in acute myocardial infarction and other disease." (PMID 34397815, 2021). "For the composite outcome of cardiovascular death, nonfatal ischemic stroke, nonfatal systemic embolism, or nonfatal myocardial infarction, 5 biomarkers including d-dimer, GDF-15, IL-6, NT-proBNP and hsTropT independently contributed to the model fit." (PMID 40744929, 2025). "In a study about myocardial infarction, cardiomyocyte-derived large EVs, but not small EVs, modulate the release of CCL2, CCL7, and IL-6 from cardiac monocytes." (PMID 40995365, 2025). "IL-6 levels are elevated in patients with ACS, including acute myocardial infarction and unstable angina, but not in stable angina." (PMID 41511355, 2025). "Activation of a trans-valvular Impella CP pump, but not VA-ECMO, before reperfusion reduced myocardial infarct size and attenuated an increase in TNF-a and IL-6 levels and MMP-9 levels and activity in the LV and renal cortex." (PMID 33782857, 2022). "This study concludes significantly elevated levels of interleukin 6 and uric acid in CAD, HTN with and without T2DM patientsmight be useful for to predict early signs of myocardial infarction." (PMID 37701509, 2022). "In a randomized control trial in patients with acute myocardial infarction, a short duration of treatment with vitamin D has significant impact on weakening the rise of CRP and IL-6 (but not TNF-α)." (PMID 32153865, 2018). "However, the exact mechanisms leading to an increase in IL-6 and CRP after myocardial infarction have not been sufficiently characterised." (PMID 32537679, 2020).
colon carcinoma (487 papers, 2003 to 2026). "This is in line with the local low expression of Mucin 2 associated with a high expression of Il6 that was previously observed in colon cancer." (PMID 40526091, 2025). "The reduction in colon cancer development was linked to decreased levels of pro-inflammatory cytokines (IL-6, TNF-α) in macrophages and inhibition of the EGFR/ERK pathway, which regulates cancer cell proliferation." (PMID 41226384, 2025). "IL-6 is transcriptionally elevated in colon cancer tissue and is associated with the risk of relapse." (PMID 39337548, 2024). "Our data suggest that the LRRK2 G2019S mutation enhances the production of IL-1β, IL-6 and IL-11 in the colon tumor microenvironment, thereby activating the NF-κB and STAT3 signaling pathways." (PMID 38607004, 2024). "In inflammation-associated colon cancer, S1P was crucial for the production of the NFκB-dependent cytokine IL-6, essential for STAT3 activation." (PMID 36672428, 2023). "They revealed that Luteolin inhibited the growth, migration, and invasion potential of SW620 and SW480 colon cancer cells caused by M1 polarization by acting on the interleukin-6 (IL-6)/signal transducer and activator of transcription 3 (STAT3) pathway." (PMID 36992138, 2023). "IL-6 is secreted by monocytes, macrophages, and colon cancer cells, and elevated serum IL-6 levels have been associated with tumor formation, dissemination, and a poor prognosis." (PMID 36139697, 2022). "Reportedly, the main causes of elevated IL-6 in colon cancer patients are tumor-associated macrophages, mesenchymal stem cells, and colon cancer-associated fibroblasts (CAF)." (PMID 35884974, 2022). "Long-term UC patients have a great risk of developing colitis-associated cancer, and TLR4/NF-κB-, TNF-α-, and IL-6-related pathways are crucial in the progression of UC to colon cancer." (PMID 36310619, 2022). "Inhibition of STAT3 or IL-6 greatly reduces the tumor burden in inflammation-associated colon cancer." (PMID 35664068, 2022). "IL-6/8 secreted by tumor-associated macrophages (TAMs) facilitated the metastasis of colon cancer in a PTP4A3-KCNN4-dependent manner." (PMID 34630392, 2021). "The main sources of IL-6 in CRC are tumor-associated macrophages, mesenchymal stem cells, and IL-6 released by colon cancer-associated fibroblasts." (PMID 33923292, 2021). "Elevated IL-6 levels have also been shown to be associated with increased invasiveness and decreased survival in other cancers, especially colon cancer." (PMID 32560494, 2020). "The same group that identified IL-6-mediated activation in inflammation, subsequently identified activation of YAP via an IL-6 mediated mechanism in colon cancer after APC gene loss." (PMID 30815737, 2019). "The elucidation of the cellular and molecular mechanisms underlying the enhancement of colon cancer stemness downstream of the IL-6/STAT3/FRA1 signaling axis opens novel opportunities to develop alternative and possibly more effective therapeutic strategies." (PMID 30804456, 2019). "In IL-6 deficient mice injected with colon cancer cells, tumor growth was decreased and dendrite cells, helper T cells and cytotoxic T-cells were increased in the tumor microenvironment." (PMID 30038723, 2018). "Kakourou with associates reported a significantly positive association between IL-6 serum level and risk of colon cancer, but the results were opposite for rectal cancer." (PMID 30154846, 2018). "Low preoperative levels of IL-6 are significantly associated with a longer disease-free survival in stage I-III colon cancer patients." (PMID 28725043, 2017). "IL-6 stimulates the progression of colon and liver cancers and elevated IL-6 levels are associated with poor prognosis in liver and colon cancers." (PMID 26883202, 2016).
colon carcinoma (continued). "We observed that participants in the highest tertile of IL-6 concentration had a statistically significant and greater than twofold higher risk of colon cancer compared to participants in the bottom tertile (Tsilidis KK, personal communication)." (PMID 26321888, 2015). "Research demonstrates the accumulation of IL-6 in colon tumors causes’ growth and increase in tumor size." (PMID 23324647, 2013). "Since high IL-6 levels are linked to tumor growth and progression in colon cancer it is logical that we also observed increased levels of pRKIP in these patients." (PMID 24098947, 2013). "Overexpression of IL-6 seems to be a hallmark of advanced tumour progression, since it has been observed, apart from colon cancer, also in other human malignancies, e." (PMID 18205904, 2008). "Accordingly, the significantly diminished growth of experimentally induced orthotopic or inflammation-associated colon tumors could be observed in IL-6-deficient mice compared to tumor development in IL-6-proficient control mice." (PMID 36428508, 2022). "It has also been reported that MSA could inhibit tumor growth in colon cancer xenografts, and this inhibition was associated with a reduction of plasma tumor necrosis factor (TNFα)/IL-6 level." (PMID 34393797, 2021). "Similarly, interleukin-6 (IL-6) has been implicated in colon cancer prognosis, metastasis, and mortality." (PMID 33917165, 2021). "The stimulating effect of DE on bacteria from the Dialister genus was also found to be inversely associated with IL-6 in humans who were fed a fiber-rich diet from whole grains; however, some reductions in Dialister species have been reported in colon cancer and Crohn’s disease." (PMID 30805695, 2020). "An anti‐tumorigenic effects of bazedoxifene, associated with reduced IL6‐dependent pSTAT3 levels, have been demonstrated in xenograft models of rhabdomyosarcoma, pancreatic, liver, and colon cancer." (PMID 30885958, 2019). "Our pathway analysis showed that metformin reduced IL-6 signaling, EMT, and colon cancer metastasis signaling; thus, we hypothesized that IL-6 also causes EMT in colon cancer, which may be inhibited by metformin." (PMID 30308035, 2018). "Moreover, elevated levels of IL-6 carry prognostic implications in certain tumor phenotypes including colon cancer, with elevated IL-6 levels closely associated with increasing tumor size, tumor stage, presence of metastatic disease and reduced survival." (PMID 30081854, 2018). "Exploring the phosphorylation of CREB and STAT3 in relation to MUC2 might reveal associations between MUC2 and IL-6 in colon cancer." (PMID 28725043, 2017). "Indeed, IL-6 has been shown to be increased in Meprin KO mice, and IL-6 has been found to be up-regulated in colon cancer tissues and significantly associated with an increased risk of relapse." (PMID 27267075, 2016). "Previous studies showed that Citrus limon peel extracts (LPE) inhibited the activity of some enzymes of the antioxidant system and reduced the interleukin-6-dependent invasiveness of gastric and colon cancer cells." (PMID 41596250, 2026). "It is also observed that senescent colon cancer cells can promote EMT in adjacent cells through IL-6, MMP-3, FGF, and HGF, potentially facilitating tumor metastasis." (PMID 41614944, 2026). "Similar effects were described by Bessler and Djaldetti, attributing to SFN the ability to exert a concentration-dependent inhibitory effect on pro-inflammatory cytokines as TNF-α and IL-6 by PMBCs co-cultured with colon carcinoma cells." (PMID 39975553, 2025). "This compound has been shown to dose-dependently inhibit the production of inflammatory cytokines such as TNF-α, IL-1β, and IL-6 in colon cancer cell cultures." (PMID 40508374, 2025).